BTD (biotinidase)
Diseases named in the same sentence as BTD in open-access papers (continued):
Sharing a sentence is not in itself a finding about the gene and the disease.
Insulin resistance (1 paper, 2019). Increased resistance towards insulin, that is, diminished effectiveness of insulin in reducing blood glucose levels. "Vitamin K epoxide reductase complex, subunit 1-like 1 (VKORC1L1), BTD, GPC1, MOCOS, GPC5, AKR1C4, and NMNAT2 are novel biomarkers for the development of insulin resistance." (PMID 30678306, 2019).
maple syrup urine disease (1 paper, 2025). An autosomal recessive inherited disorder caused by mutations in the BCKDHA, BCKDHB, DBT, and DLD genes. "Urine specimens from individuals with biotinidase deficiency, maple syrup urine disease (MSUD) and ketotic hypoglycemia were analysed to demonstrate the potential clinical impact." (PMID 39447825, 2025).
multiple sclerosis (1 paper, 2021). A progressive autoimmune disorder affecting the central nervous system resulting in demyelination. "In addition to NMOSD, mitochondrial disease, multiple sclerosis, transverse myelitis, and brainstem encephalitis may also present as biotinidase deficiency." (PMID 35265569, 2021).
nephropathies (1 paper, 2023). "The decision tree highlights two proteins (MRC1 and BTD) which, among all the proteins which resulted deregulated in the two groups, could be possible candidates in helping to discriminate IMN disease from other types of nephropathies." (PMID 37511514, 2023). "Finally, the proteomic tree clustering highlighted two proteins (MRC1 and BTD) which, among all the proteins which resulted deregulated in the two groups, could be possible candidates in helping to discriminate IMN disease from other types of nephropathies." (PMID 37511514, 2023). "Based on our knowledge, there are no studies regarding BTD involvement in IMN disease and this is the first time that this protein seems to be correlated to the specificity of the IMN compared to other nephropathies." (PMID 37511514, 2023).
nephrotic syndrome (1 paper, 2023). A collection of symptoms that include severe edema, proteinuria, and hypoalbuminemia; it is indicative of renal dysfunction. "In addition, based on a supervised classification tree, two possible candidates (MRC1 and BTD) among the deregulated protein panel showed the ability to distinguish IMN from other nephrotic syndromes with a sensitivity of 93% and a specificity equal to 100%." (PMID 37511514, 2023).
neurofibromatosis (1 paper, 2022). A hereditary neoplastic syndrome in which tumors grow in the nervous system. "This includes those linked to biotinidase deficiency (Chi-squared test P < 1 x 10−7), neurofibromatosis (P = 1.8 x 10−5) and glycogen storage in cattle (P = 3 x 10−7) and factor VII deficiency in pigs (P < 1 x 10−7)." (PMID 36131008, 2022).
papillary thyroid cancer (1 paper, 2012). "Immunohistochemical analysis of biotinidase was carried out in 129 papillary thyroid cancer (PTC, 34 benign thyroid tissues and 43 FNA samples and correlated with patients’ prognosis." (PMID 22911723, 2012). "Furthermore, the potential applicability that biotinidase presents as an aid to FNA diagnosis sets the stage for improving the management of aggressive papillary thyroid cancer and providing hope anew to patients and clinicians alike." (PMID 22911723, 2012).
pyridoxine-dependent epilepsy (1 paper, 2020). A rare neurometabolic disease characterized by recurrent intractable seizures in the prenatal, neonatal and postnatal period that are resistant to anti-epileptic drugs (AEDs) but that are responsive to pharmacological dosages of pyridoxine (vitamin B6). "Pyridoxine-dependent epilepsy and biotinidase deficiency are some paramount examples.Many of these disorders are amenable to specific treatment (97/373), and timely and accurate diagnosis is necessary to prevent the irreversible outcomes." (PMID 32256626, 2020).
seborrheic dermatitis (1 paper, 2022). A chronic, inflammatory skin disorder that affects the scalp, central face and skin folds; it is characterized by scaling and itching. "In addition, individuals homozygous for the p.Asp444His variant have been reported, who had enzyme activity that excluded the diagnosis of biotinidase deficiency, but who developed symptoms of the disease—skin lesions (severe diaper dermatitis, seborrheic dermatitis)." (PMID 35627187, 2022).
tetraplegia (1 paper, 2022). "We found a description of a patient with a late-onset biotinidase deficit, diagnosed symptomatically, who presented with optic nerve atrophy and tetraplegia." (PMID 35627187, 2022).
thyroid (1 paper, 2012). "We analyzed the expression of biotinidase in 23 benign and 20 malignant thyroid FNA samples." (PMID 22911723, 2012). "The corroborative evidence from aggressive phenotypes of cancers other than thyroid further eludes to a potential role that biotinidase might play in the general mechanism of cancer aggressiveness." (PMID 22911723, 2012).
thyroid cancer (1 paper, 2012). "In conclusion, loss of overall biotinidase expression is a novel marker for thyroid cancer aggressiveness." (PMID 22911723, 2012). "In aggressive thyroid cancer, there was significant reduction in overall biotinidase expression (p = 0.001) at both nuclear (p<0.001) and cytoplasmic (p = 0.002) levels as compared to non-aggressive thyroid tumors." (PMID 22911723, 2012). "All the benign FNA sections showed nuclear expression (23/23, 100%) of biotinidase protein as compared to thyroid cancer sections (13/20, 65%; p = 0.002)." (PMID 22911723, 2012). "The goal of the current study was to analyze the expression of biotinidase in thyroid cancer tissues and fine needle aspiration (FNA) samples to evaluate its diagnostic and prognostic potential in thyroid cancer." (PMID 22911723, 2012). "Intriguingly, one of the genes in their panel was biotinidase, down regulated in pelvic lymph node metastasis, akin to our findings in thyroid cancer." (PMID 22911723, 2012). "Upon stratification of cancer into aggressive and non-aggressive tumors, reduced overall, nuclear and cytoplasmic expression of biotinidase was observed in aggressive thyroid cancers with AUC values of 0.715, 0.696 and 0.347 respectively." (PMID 22911723, 2012). "Correlation of biotinidase expression with clinico-pathological parameters of thyroid cancer patients." (PMID 22911723, 2012). "Cytoplasmic expression of biotinidase was observed in 6/23 (26.1%) benign cases as compared to 2/20 (10%) in thyroid cancer cases (p = 0.25, OR = 0.315, 95% C.I. = 0.056−1.78)." (PMID 22911723, 2012). "This novel use of biotinidase underscores its potential to serve as a tool to identify aggressive thyroid cancers in early stages for more focused therapy." (PMID 22911723, 2012). "The follow-up data of 116 thyroid cancer patients for up to 19.5 years were used to assess the prognostic relevance of biotinidase for predicting recurrence in these patients after completion of primary treatment." (PMID 22911723, 2012). "Expression of overall and nuclear biotinidase in benign FNA samples and its loss in malignant cases, specifically in aggressive thyroid cancers, corresponds to the pattern observed in thyroid cancer tissues." (PMID 22911723, 2012). "The exploration of the relationship between reduced biotinidase, BRAF (V600E) mutation and aggressive thyroid cancers as well as with disease prognosis in larger independent cohorts of this malignancy will constitute the subject of future studies." (PMID 22911723, 2012). "Nevertheless, the findings of our study indicate decrease in biotinidase levels in aggressive thyroid carcinomas." (PMID 22911723, 2012). "Biotinidase was identified in secretome analysis of thyroid cancer cell lines using proteomics." (PMID 22911723, 2012). "Additional work in this area could shed crucial light on the mechanism of aggressiveness in thyroid cancer as well as aid the discovery of novel mechanism(s) that may account for the potential of biotinidase to determine aggressiveness of thyroid cancer." (PMID 22911723, 2012). "In addition, our study demonstrates biotinidase levels are decreased in aggressive thyroid carcinomas and suggests its potential to serve as a marker for tumor aggressiveness." (PMID 22911723, 2012). "However, this does not undermine the relevance of our study, which is the first to highlight the link between biotinidase and thyroid cancer and among the few that illustrate and strengthen the burgeoning evidence implicating biotinidase as a factor in cancer aggressiveness." (PMID 22911723, 2012). "The clinical relevance was suggested by demonstrating reduced levels of biotinidase in aggressive thyroid cancer patients’ sera as compared to the non-aggressive and benign patients’ sera by western blotting." (PMID 22911723, 2012). "Receiver operating characteristic curve analysis of biotinidase expression in benign vs malignant and aggressive vs non-aggressive thyroid cancer." (PMID 22911723, 2012).
thyroid cancer (continued). "Low level of biotinidase was observed in aggressive anaplastic derived cell line (CAL-62) as compared to the non-aggressive papillary derived thyroid cancer cell line (TPC-1)." (PMID 22911723, 2012). "Upon comparison of aggressive and non-aggressive thyroid cancers, overall biotinidase expression reduced in the former (5/7, 71.4%) compared to the latter (2/13, 15.4%, p = 0.022)." (PMID 22911723, 2012). "Similarly, reduced cytoplasmic expression of biotinidase was observed in aggressive (7/7, 100%) thyroid cancer cases as compared to the non-aggressive cases (11/13, 84.6%, p = 0.521)." (PMID 22911723, 2012).
thyrotoxicosis (1 paper, 2022). A hypermetabolic syndrome caused by the elevation of thyroid hormone levels in the serum. "In the present study, the abundance of Biotinidase (Btd), Transcobalamin II (Tcn2), vitamin D binding protein (VDBP, Gc), Afamin (Afm), Vitamin K-dependent protein C (Proc), and Vitamin K-dependent protein Z (Proz) were downregulated in thyrotoxicosis mice." (PMID 35720307, 2022).
Wilson disease (1 paper, 2023). A very rare inherited multisystemic disease presenting non-specific neurological, hepatic, psychiatric or osseo-muscular manifestations due to excessive copper deposition in the body. "The most frequent in the ACMG PFs were BTD biotinidase deficiency, APT7B Wilson disease, and GAA Pompe disease." (PMID 36635046, 2023).
cancer (10 papers, 2010 to 2026). A tumor composed of atypical neoplastic, often pleomorphic cells that invade other tissues. "Whether the loss of biotinidase plays a functional role or is associated with cancer aggressiveness remains to be addressed in future studies." (PMID 22911723, 2012). "In the Tin list, this concerns the genes BDNF Antisense RNA (BDNF-AS), Biotinidase (BTD), Metastasis-Associated Lung Adenocarcinoma Transcript 1 (MALAT1), MicroRNA 210 (MIR210), and Prostate Cancer-Associated Transcript 1 (PCAT1)." (PMID 37736859, 2023). "Loss of overall and nuclear as well as increased cytoplasmic expression of biotinidase distinguished benign tissues from malignant tumors with AUC values of 0.816, 0.972 and 0.662 respectively." (PMID 22911723, 2012). "Receiver operating characteristic curve analysis was used to determine the potential of biotinidase expression as a biomarker to distinguish benign nodules and malignant tumors." (PMID 22911723, 2012). "Nevertheless, our findings are of significance in view of the limited studies on biotinidase in human cancers; importantly these few reports corroborate and support our observations." (PMID 22911723, 2012). "Biotinidase (BTD) and holocarboxylase synthetase (HCS) are the enzymes responsible for biotinylation homeostasis, while deregulation of this process has been associated to various cancers development." (PMID 34948252, 2021). "The role biotinidase plays in cancer aggressiveness remains to be elucidated." (PMID 22911723, 2012). "The functional significance of biotinidase in development and/or progression of cancer remain unknown." (PMID 22911723, 2012). "To confirm the impact of altered ECM1, MBL2, BTD and RAB5C expression in existing clinical patient studies, we analysed four biomarker‐altered and non‐altered groups with a survival of 1084 patients in the pan‐cancer atlas and 2509 patients in the METABRIC data." (PMID 40545963, 2025). "In the current study, our main objective was to determine the clinical significance of biotinidase as a marker to distinguish benign thyroid and malignant tumors as well as to stratify aggressive and non-aggressive PTC that could serve as a potential tool for improved management of this malignancy." (PMID 22911723, 2012).
metabolic disorder (7 papers, 2013 to 2025). "Biotinidase (BTD) deficiency (OMIM 253260) is an autosomal recessively inherited metabolic disorder resulting from deficient activity of the BTD enzyme, which can cleave and release biotin from a variety of biotin-dependent carboxylases, and is therefore recognized as a tool to recycle biotin." (PMID 37373384, 2023). "Biotinidase (BTD) deficiency (OMIM 253260), as a rare autosomal recessively inherited metabolic disorder, is closely associated with disturbances in the hydrolysis of small biotinylated peptides and biocytin, as well as the consequent failure in biotin liberation and recycling." (PMID 37373384, 2023).
tumor (4 papers, 2012 to 2025). "The association of reduction in nuclear and cytoplasmic biotinidase to these clinical parameters provides additional credibility to the loss of overall biotinidase correlating significantly with tumor aggressiveness (p = 0.001)." (PMID 22911723, 2012). "Upon stratification into nuclear and cytoplasmic subcellular compartments, 84/129 cases (65.1%) showed loss of nuclear biotinidase and 87/129 (67.4%) showed increased cytoplasmic expression in tumor cells." (PMID 22911723, 2012). "Classically age, gender, tumor stage, extrathyroidal extension (spread outside the thyroid capsule), nodal status, histology type, histology grade all have prognostic significance and were observed to be associated with biotinidase expression in our study." (PMID 22911723, 2012). "IHC analysis of paired tumour tissue samples from 10 patients confirmed the expression of four markers (BTD, ECM1, MBL2, and RAB5C) in both blood and tissues, as demonstrated in our study." (PMID 40545963, 2025). "PTC and FTC tumours presented a group of common dysregulated proteins including SOD3, ISLR, biotinidase, polymerase I and transcript release factor (cavin-1), TFF3, alpha(B)-crystallin (CryAB), AGR2, tenascin and 14-3-3 gamma." (PMID 27025787, 2016).
inborn errors of metabolism (2 papers, 2022 to 2024). An inherited disorder resulting from an enzyme defect in biochemical and metabolic pathways affecting proteins, fats, carbohydrates metabolism or organelle function. "Moreover, functional enrichment analysis by STRING showed that BTD, ASL, GBE1 and AGL are among 726 genes co-expressed during inherited metabolic disorder." (PMID 38592052, 2024).
autosomal recessive disease (1 paper, 2025). Autosomal recessive form of disease. "In Family K, a pathogenic variant (c.1495C > T; p.Pro499Ser) was detected in the biotinidase (BTD) gene, which is associated with autosomal recessive disease." (PMID 41189009, 2025).
endocrine disorders (1 paper, 2024). "We provide updated data on the incidence of various IEM and endocrine disorders among the Saudi population and highlight the role of false positive results of biotinidase activity that can dramatically increase the recall rate and lead to an overestimation of the incidence data." (PMID 39449360, 2024).
infection (1 paper, 2022). The state of being infected such as from the introduction of a foreign agent such as serum, vaccine, antigenic substance or organism. "Fourteen proteins, including three apolipoproteins, two globins, complement component 3 (C3), ceruloplasmin and biotinidase, were negatively correlated with the infection intensity." (PMID 36088326, 2022).
BTD also shares sentences with these, for which no sentence is quoted: congenital adrenal hyperplasia (4 papers); phenylketonuria (4); genetic diseases (2); mitochondrial disease (2); 21-hydroxylase deficiency (1); acute tubular necrosis (1); Alport syndrome (1); Alstrom syndrome (1); Ataxia (1); atopic dermatitis (1); C3 glomerulopathy (1); Cerebral folate deficiency (1); Clouston syndrome (1); congenital hypothyroidism (1); corneal dystrophy (1); dentinogenesis imperfecta (1); dermatophytosis (1); Encephalopathy (1); end stage renal disease (1); erythrokeratodermia variabilis (1); failure of kidney (1); Fanconi anemia (1); fungal infections (1); glycine encephalopathy (1); glycogen storage disease II (1); Hartnup disease (1); Hearing impairment (1); hemoglobinopathies (1); hereditary hemochromatosis (1); Hypertonia (1).
A further 27 diseases each share a sentence with BTD in 1 paper.